HOXA2 (homeobox A2)
Description:
Sequence-specific transcription factor which is part of a developmental regulatory system that provides cells with specific positional identities on the anterior-posterior axis.
Synonyms: HOX1K; MCOHI
Tractability: No criterion of Open Targets' tractability assessment is met for any kind of drug.
Gene: Protein-coding gene on chromosome 7 (27,100,354 to 27,102,686, reverse strand). Ensembl gene ENSG00000105996.
Subcellular location: Nucleus
Subcellular location (Human Protein Atlas): Nucleoplasm; Vesicles
Pathways (Reactome):
Developmental Biology: Activation of anterior HOX genes in hindbrain development during early embryogenesis; Regulation of expression of SLITs and ROBOs
Gene Ontology:
Molecular function: sequence-specific double-stranded DNA binding; DNA-binding transcription factor activity, RNA polymerase II-specific; RNA polymerase II cis-regulatory region sequence-specific DNA binding; DNA binding; DNA-binding transcription factor activity; DNA-binding transcription repressor activity, RNA polymerase II-specific; sequence-specific DNA binding
Biological process: regulation of transcription by RNA polymerase II; embryonic skeletal system development; muscle structure development; negative regulation of transcription by RNA polymerase II; pharyngeal system development; regulation of DNA-templated transcription
Cellular component: chromatin; nucleus
Genetic constraint (gnomAD): Loss-of-function variants: 4 observed, 27.4 expected, observed/expected ratio (o/e) 0.15, 90% interval 0.071 to 0.33. The upper end of that interval is the gene's LOEUF score, 0.33, which puts it in group 1 of 6, group 1 being the genes least tolerant of losing a copy. Missense variants: 430 observed, 477.07 expected, observed/expected ratio (o/e) 0.9, 90% interval 0.83 to 0.98. Synonymous variants: 200 observed, 204.95 expected, observed/expected ratio (o/e) 0.98, 90% interval 0.87 to 1.1.
Homologues: Orthologues: chimpanzee HOXA2 (100% identical), macaque HOXA2 (98% identical), pig HOXA2 (98% identical), guinea pig HOXA2 (97% identical), dog HOXA2 (97% identical), mouse Hoxa2 (95% identical), rabbit HOXA2 (94% identical), rat Hoxa2 (94% identical). Paralogues in human: HOXB2 (47% identical), HOXA3 (25% identical), HOXD3 (25% identical), HOXB3 (24% identical), HOXA1 (19% identical), PDX1 (19% identical), HOXD4 (19% identical), HOXB4 (18% identical), TLX1 (18% identical), HOXB1 (17% identical), HOXA4 (17% identical), HOXB5 (17% identical), and 30 more.
Diseases named in the same sentence as HOXA2 in open-access papers:
HOXA2 is named in the same sentence as 50 diseases in open-access papers, as found by Europe PMC text mining. Sharing a sentence is not in itself a finding about the gene and the disease. The quoted sentences say what the papers report.
microtia (11 papers, 2012 to 2025). "HOXA2 plays a critical role in the development of the second branchial arch and mutations are linked to autosomal recessive microtia, directly affecting auricle formation." (PMID 40310042, 2025). "Mutations in the HOXA2 gene have been identified in individuals with microtia and associated craniofacial abnormalities." (PMID 38594752, 2024). "Nevertheless, TCOF1 and HOXA2, in turn, cause microtia in a dominant manner, suggesting haploinsufficiency, while HSPA9 and GSC are in recessive mode of inheritance." (PMID 38594752, 2024). "Identifying the association between HOXA2 variants and microtia provides essential insights into the genetic mechanisms underlying this condition." (PMID 38594752, 2024). "Studies have also shown that patients with mutations in HOXA2 display severe microtia, middle ear deformities and hearing loss." (PMID 36861077, 2023). "A small number of studies have also focused on the HOXA2 gene as a genetic cause of isolated microtia." (PMID 28968992, 2017). "This study showed different results from a previous study that found three genes most related to the development of microtia HOXA2, followed by FGF3 and TCOF1, the third most common genes." (PMID 38594752, 2024). "The HOXA2 gene was found (8.33%) in this study as non-syndromic microtia cases." (PMID 38594752, 2024). "To date, only HOXA2 mutations have been reported as responsible for isolated bilateral microtia with or without hearing loss in humans." (PMID 32552830, 2020). "HOXA2 is the only reported gene responsible for isolated microtia to date." (PMID 32552830, 2020). "Identification of pathogenic mutations in HOXA2 was reported in three different isolated bilateral microtia families, prompting researchers to propose that HOXA2 may be among genes responsible for the pathogenesis of isolated microtia." (PMID 28968992, 2017). "HOXA2 mutations were reported in patients with isolated bilateral microtia without hearing loss." (PMID 32552830, 2020). "However, studies that have focused on sporadic microtia patients have found no pathogenic mutations in HOXA2." (PMID 28968992, 2017). "In the non-syndromic microtia group, the most frequently found gene was GSC exon 2 (25%; 6) and FANCB (16.67%); HOXA2, GSC exon 3, MARS1, CDT1 were found respectively in two (8.33%) cases." (PMID 38594752, 2024). "However, when we scanned the seven cnLOH regions for phenotypes entered in OMIM, we identified only one autosomal recessive hearing loss phenotype (OMIM #612290: microtia, hearing impairment, and cleft palate caused by HOXA2 mutations), which did not match the phenotype of our patient." (PMID 22887808, 2012). "In the syndromic microtia group, the most common genes were TCOF1 (43.75%), SIX2 (4.69%), and HSPA9 (4.69%), while in the non-syndromic microtia group, the most frequently found gene was GSC exon 2 (25%), FANCB (16.67%), HOXA2 (8.33%), GSC exon 3 (8.33%), MARS1 (8.33%), and CDT1 (8.33%)." (PMID 38594752, 2024). "Based on our findings, 64 cases (72.72%) were syndromic microtia [TCOF1 (43.75%), SIX2 (4.69%), and HSPA9 (4.69%)] and 24 cases (27.27%) were non-syndromic microtia [GSC exon 2 (25%), FANCB (16.67%), HOXA2 (8.33%), GSC exon 3 (8.33%), MARS1 (8.33%), CDT1 (8.33%)]." (PMID 38594752, 2024).
glioma (10 papers, 2021 to 2025). A benign or malignant brain and spinal cord tumor that arises from glial cells (astrocytes, oligodendrocytes, ependymal cells). "Abnormal DNA methylation of HOXA2 promoter regions causes dysregulation of gene expression, therefore influencing the invasion, prognosis, and clinical characteristics of colorectal cancer, glioma, and nasopharyngeal carcinoma." (PMID 33816499, 2021). "They found that HOXA2 was significantly increased and associated with lncRNA HOTAIRM1 like HOXA1 in glioma." (PMID 37351805, 2023). "Many HOMEOBOX (HOX)-related genes (HOXD11, HOXD9, HOXC10, HOXC11, HOXC6, HOXB3, HOXA2, HOXA1) were associated with a glioma grade and significantly overexpressed in GIV (Wilcoxon rank-sum and BH padj < 0.05)." (PMID 36850002, 2023). "Liu's research also validated the prognostic value of HOXA2 in glioma patients using Kaplan–Meier analysis with multivariate analysis in CGGA and a single Kaplan–Meier analysis in TCGA." (PMID 37351805, 2023). "In conclusion, a risk model constructed by 6 hypoxia-driven genes (WT1, HOXA2, HOXC6, MMP9, SHOX2 and MYOD1) provide valuable clinical utility for the prognostic prediction of glioma patients." (PMID 36118887, 2022). "Among them, 22 genes had a degree score ≥10 and 6 genes (WT1, HOXA2, HOXC6, MMP9, SHOX2 and MYOD1) were selected to construct a signature to classify glioma patients into low- or high-risk groups." (PMID 36118887, 2022). "We identified five critical genes (HOXA2, CHI3L1, POSTN, OASL, and ZNF474) with substantial roles in the glioma context." (PMID 38473752, 2024). "Utilizing bioinformatics tools such as GSEA and the Chinese Glioma Genome Atlas (CGGA), an analysis was conducted to investigate the impact of HOXA2 on glioma progression." (PMID 38311789, 2024). "Hox genes (HOXA2, HOXA5, and HOXA7) can regulate several hallmarks of cancer in malignant glial tumors." (PMID 37397378, 2023). "We further demonstrated that the over-expression of HOXA2 was significantly related to the IDH wild-type of GBM, which was also revealed in studies about glioma." (PMID 37351805, 2023). "We also confirmed the higher expression of HOXA2 in GBM samples, consistent with the results from studies related to glioma." (PMID 37351805, 2023). "Heatmap analysis showed that WT1, HOXA2, HOXC6, MMP9 and SHOX2 are highly expressed in high-hypoxia glioma tissues in the TCGA, whereas MYOD1 expression is reduced." (PMID 36118887, 2022). "Similarly, we found that the expression of HOXC6, MMP9 and SHOX2 was higher in recurrent glioma tissues compared with primary glioma tissues and the expression of MYOD1 was decreased, while there were no significant changes in WT1 and HOXA2." (PMID 36118887, 2022).
prostate carcinoma (10 papers, 2019 to 2024). A carcinoma that arises from epithelial cells of the prostate gland. "However, recent work showed that HOXA2 is associated with aggressive prostate cancer, underlining the robustness of our data." (PMID 36611993, 2023). "It has been reported that during the progression of prostate cancer (PCa), aberrantly expressed HOXA2, HOXA9, and HOXA10 facilitate the infiltration of dendritic cells, macrophages, and mastocytes." (PMID 38904676, 2024). "In another study on prostate cancer, HOXA2, HOXA9, and HOXA10 were identified as critical genes, which were both abnormally expressed and associated with clinical outcomes of patients with prostate cancer." (PMID 36159969, 2022). "The SNP, rs11672691, resides in an active enhancer element and the risk G allele increases the chromatin binding of HOXA2, which subsequently promotes the expression of PCAT19 and CEACAM21, which may contribute to the aggressive phenotype of prostate cancer." (PMID 31013831, 2019). "More specifically, the risk allele rs11672691-G enhances the binding activity of the novel transcription factor HOXA2, which in turn regulates expression of PCAT19 in prostate cancer through enhancer–promoter loop formation." (PMID 34449663, 2021).
cleft palate (5 papers, 2009 to 2021). Cleft palate is a fissure type embryopathy that affects the soft and hard palate to varying degrees. "Mutation in the Hoxa2 gene is associated with cleft palate in humans and mouse models." (PMID 29184513, 2017). "Our findings that Hoxa2 is also expressed in these extrinsic tongue muscles raises the possibility that the loss of Hoxa2 may directly cause tongue muscle defects leading to cleft palate." (PMID 19325874, 2009). "Defects in musculoskeletal anchoring of the tongue that would impair tongue function are correlated with cleft palate in Hoxa2 mutant mice." (PMID 31300413, 2019). "Hoxa2−/− mice exhibit cleft palate; however, the cellular and molecular mechanisms leading to cleft palate in Hoxa2−/− mice is largely unknown." (PMID 29184513, 2017). "Our data argue that improper BMP signaling leading to the increased osteoprogenitor cell proliferation and commitment could be a reason for the cleft palate pathogenesis in the Hoxa2−/− mice." (PMID 29184513, 2017).
colorectal cancer (4 papers, 2019 to 2022). A primary or metastatic malignant neoplasm that affects the colon or rectum. "Notably, we found that the highest methylation of HOXA5 and HOXA2 occurs in early stage colorectal cancer tissues such as stage I and II, N0, MO, and non-invasive." (PMID 31165042, 2019). "Notably, we found that the highest methylation of HOXA5 and HOXA2 occurs in the early stages of colorectal cancer tissues such as stage I, N0, MO, and non-invasive tissues." (PMID 31165042, 2019). "In colorectal cancer, the percentage of methylation of three HOXA genes (HOXA5, HOXA2, and HOXA6) were up to 67.62%, 58.36%, and 31.32%, respectively." (PMID 36159969, 2022). "This indicated that hypermethylation of HOXA5, HOXA2, and HOXA6 is an important event in colorectal cancer." (PMID 31165042, 2019). "In this article, based on the latest colorectal cancer database and our experiments, we analyze the methylation status in three HOXA genes including HOXA2, HOXA5, and HOXA6 and its clinical application." (PMID 31165042, 2019). "HOXA5, HOXA2, and HOXA6 are frequently methylated, and this leads to silencing of these genes and progression of colorectal cancer." (PMID 31165042, 2019). "Similar to this result, downregulation was also observed for the HOXA2 and HOXA6 genes in large-scale human colorectal cancer expression databases." (PMID 31165042, 2019). "Furthermore, the highest methylation of HOXA5 and HOXA2 was detected in the early stages of colorectal cancer including stage I, N0, MO, and no perineural invasion." (PMID 31165042, 2019).
colon cancer (3 papers, 2022 to 2023). "Congruent with these observations, H3K27me3 was enriched at the promoter and coding regions of ARL14 and HOXA2 genes in SW620 colon cancer cells but largely disappeared following B32B3 and Taz treatment." (PMID 37069142, 2023). "The HOXA cluster (HOXA2/3/6) has been identified as hypermethylated in breast and colon cancer." (PMID 37628872, 2023).
oral cancer (3 papers, 2012 to 2025). "While HOXA2 was upregulated in dysplasia but lost during the development of oral cancer, HOXB2 expression was downregulated in both dysplasia and primary tumor." (PMID 35710803, 2022). "In healthy oral mucosa derived from patients without risk factors for oral cancer, only HOXA1, HOXA2 and HOXA4 were expressed, whereas the abundance of transcripts in histologically normal-looking oral mucosa near OSCC and in OSCC samples was higher." (PMID 22498108, 2012).
cervical cancer (2 papers, 2021 to 2022). A primary or metastatic malignant neoplasm involving the cervix. "The rest of the HOXA members (including HOXA2‐9 and HOXA13) showed very small differences between cervical cancer and normal controls, with no statistical significance." (PMID 34606634, 2021).
lung carcinoma (2 papers, 2018 to 2021). "HOXA2, HOXA3, and HOXA5 have been recognized as target for DNA methylation in lung cancer, and they promoted carcinogenesis, but also acted as tumor-suppressor factors." (PMID 34262872, 2021).
multiple myeloma (2 papers, 2021 to 2022). "Specifically, we found that healthy MSCs exposed to MM cells underwent gains (HOXA9, ACVR2A, EBF2) and losses (HOXA2, HOXA3, HOXC5) of DNA methylation in the direction of those observed for MSCs from myeloma patients." (PMID 33462210, 2021). "Some of these TFs were specifically downregulated in MSCs of active myeloma (RUNX2 and TEAD2), others were already downregulated in precursor myeloma stages (HOXC9 and CEBPD), whereas other TFs, including HOXA2 and ATF3, did not change their expression in any myeloma stages." (PMID 33462210, 2021).
orofacial cleft (2 papers, 2017 to 2024). A disorder of facial skeleton that is characterized by cleft lip and/or cleft palate that result in feeding, speech and hearing problems caused by failures during development. "In the investigation of orofacial cleft, distinct methylation patterns were observed for different subtypes of orofacial cleft within the HOXA2 gene." (PMID 38311789, 2024). "Several regions mapped to genes that have previously been implicated in the development of orofacial clefts (for example, TBX1, COL11A2, HOXA2, PDGFRA), and over 250 associations were novel." (PMID 28603561, 2017).
allergic disease (1 paper, 2025). An immune response that occurs following re-exposure to an innocuous antigen, and that requires the presence of existing antibodies against that antigen. "However, HOXA2 has not been previously linked to allergic diseases or immune tolerance, but other members of the HOX gene family have demonstrated regulatory roles in type 2 immune responses." (PMID 41394805, 2025).
asthma (1 paper, 2025). "Notably, the high-expression group of HOXA2 was linked to distinct immunopathological processes, such as those involved in asthma pathogenesis, complement and coagulation cascades, extracellular matrix (ECM)-receptor interaction, and systemic lupus erythematosus markers." (PMID 41415292, 2025).
brain cancer (1 paper, 2020). A primary or metastatic malignant neoplasm affecting the brain. "Notably, there were 6 HOX genes, namely HOXA2, HOXA4, HOXB2, HOXB3, HOXB4, and HOXC4, which changed expression only in brain cancer (either in GBM, brain lower grade glioma (LGG), or in both)." (PMID 32545894, 2020).
chronic myeloid leukemia (1 paper, 2009). "Examples include a study on chronic myeloid leukemia stem cells, which showed that HH-dependent Stat3 activation orchestrates down-regulation of Hox genes such as HoxA2 and HoxB4." (PMID 19575820, 2009).
colorectal adenocarcinoma (1 paper, 2019). The most common type of colorectal carcinoma. "Methylation level of each CG site in the CpG island regions of HOXA2 gene in 9 paired colorectal adenocarcinoma samples and adjacent non-tumor colonic tissue samples." (PMID 31165042, 2019).
glioblastoma multiforme (1 paper, 2022). "LncRNA HOTAIRM1 (HOX antisense intergenic RNA myeloid 1), which is located between the HOXA1 and HOXA2 genes, could interact with DNMTs and other epigenetic factors to sequester them away from HOXA1 promoter in glioblastoma multiforme (GBM)." (PMID 36533073, 2022).
hepatitis B (1 paper, 2022). "In addition to cancers, the CpG methylation of HOXA2 was related to severe fibrosis and the progression in hepatitis B-related chronic liver disease." (PMID 36159969, 2022).
idiopathic pulmonary fibrosis (1 paper, 2022). Idiopathic pulmonary fibrosis (IPF) is a nonneoplastic pulmonary disease that is characterized by the formation of scar tissue within the lungs in the absence of any known cause. "The low-methylation epigenotype of HOXA2 and HOXA9 in squamous cell carcinoma was associated with idiopathic pulmonary fibrosis and poorer prognosis." (PMID 36159969, 2022).
liver cancer (1 paper, 2023). An epithelial or non-epithelial malignant neoplasm that arises from the liver. "Studies have shown that the expression of the Hoxa2 in liver cancer samples is significantly upregulated, and in the progression of mild fibrosis and severe fibrosis, Hoxa2 DNA methylation is significantly increased." (PMID 37047411, 2023).